TYMP (thymidine phosphorylase)
Diseases named in the same sentence as TYMP in open-access papers (continued):
Sharing a sentence is not in itself a finding about the gene and the disease.
cancer (76 papers, 1998 to 2026). A tumor composed of atypical neoplastic, often pleomorphic cells that invade other tissues. "TYMP up-regulation is associated with pro-tumor functions such as cancer cell proliferation, metabolic alterations, and increased angiogenesis." (PMID 40519286, 2025). "To study the functional implication of the risk gene (TYMP) in cancer development, we performed a pan-cancer analysis." (PMID 35250999, 2022). "The radar plot displayed the association of TYMP expression with MSI in several cancers, including KIRC." (PMID 35250999, 2022). "On the other hand, higher levels of TYMP-encoded protein in cancer cells appear rather beneficial for capecitabine treatment as thymidine phosphorylase catalyzes the conversion of an inactive prodrug to 5FU inside the cancer cell." (PMID 35922756, 2022). "An increased expression of TYMP is frequently associated with the aggressiveness of cancer with a poor prognosis." (PMID 34589604, 2021). "TYMP protein is associated with pro-angiogenic and anti-apoptotic effects in cancer cells, and higher levels of TYMP in RCC tissue versus non-neoplastic kidney tissues have also been described." (PMID 34482820, 2021). "High levels of TYMP have been reported in the liver, lung and breast tumors and associate with poor prognostic outcome of cancer patients." (PMID 25881156, 2015). "Understanding TYMP’s anti-apoptotic role could enhance cancer therapies and offer insights into treating diseases caused by cellular hypoxia." (PMID 40303404, 2025). "In addition, we evaluated the associations between the expression of TYMP and the levels of TMB and noticed that the mRNA level of TYMP was linked to several cancers, including KIRC." (PMID 35250999, 2022). "However, more data are needed to better understand their roles: as reported, the deep deletion is the most common TYMP mutation among cancers, leading to a complete loss of expression, while in GC we reported four missense mutations." (PMID 32887417, 2020). "An assay on the cancer-related enzyme thymidine phosphorylase was set up, and IC50 values for different inhibitors covering the range from nM to hundreds of μM were determined." (PMID 42085525, 2026). "The link between MNGIE and altered TYMP activity prompted an investigation into the mechanisms linking thymidine metabolism to mitochondrial function in other contexts, such as cancer." (PMID 40519286, 2025). "Although challenges exist—such as the potential disruption of normal physiological functions when inhibiting TYMP—the protein remains a promising target for cancer treatment." (PMID 40303404, 2025). "It holds considerable potential in the understanding and treatment of cancer, making ongoing research into TYMP essential." (PMID 40303404, 2025). "Many cancers utilize TYMP-mediated pathways to form 2-deoxyribose that can fuel biosynthetic processes." (PMID 40519286, 2025). "Despite existing limitations, further research on TYMP holds significant potential for advancing cancer treatment." (PMID 40303404, 2025). "TYMP also serves as a valuable immune prognostic marker in various cancers, including renal clear cell carcinoma and low-grade glioma." (PMID 40303404, 2025). "High levels of TYMP expression can diminish the effectiveness of 5-FU, resulting in reduced efficacy against cancer." (PMID 39548315, 2025). "Overexpression of HO-1 resulted in the upregulation of proangiogenic enzyme thymidine phosphorylase, which significantly elevates angiogenesis in cancer cells, but in in vitro, it suppressed the proliferation and migration of cancer cells." (PMID 39309448, 2024). "In the final step in the activation pathway, 5-FU is catalyzed by thymidine phosphorylase (TP), which is present in high concentrations in cancer cells." (PMID 38538985, 2024).
cancer (continued). "The TYMP is found to beoverexpressed in various cancer types, encompassing head and neck, breast,lung, oral squamous carcinoma, esophageal, gastric, colorectal,bladder, prostate, ovarian,and cervical cancers, among several others." (PMID 38712004, 2024). "Some hydrazones, for example, have been examined as a new class of dual inhibitors of thymidine phosphorylase and cancer cell growth, which merits further investigation for anti-cancer drug development." (PMID 35956675, 2022). "It has been reported that the activity of cancer-promoting gene Thymidine Phosphorylase (TP) is necessary for the activation of various chemotherapeutic agents." (PMID 36295086, 2022). "This group also showed that the TYMP activity and improved efficacy of Capecitabine in various human cancer xenografts can be induced by different treatment regimen including ionizing radiation, oxaliplatin, and chemoendocrine therapy." (PMID 33874986, 2021). "Capecitabine is a novel tablet form of fluoropyrimidine that can more easily transform into 5-fluorouracil (5-FU) by thymidine phosphorylase (TP) in cancer cells." (PMID 32719436, 2020). "Cancer cells have relatively high levels of CDA and TYMP, explaining the increased sensitivity of cancer cells to CPBN, and the low adverse effects of this drug on non-tumoral tissues." (PMID 30740528, 2019). "5’-DFUR is converted to its active and toxic form 5-FU through metabolic conversion by thymidine phosphorylase (TP), a gene overexpressed in many cancer types." (PMID 30551585, 2018). "Sequential exposure to paclitaxel following 5-FU exerted additive cytotoxic effects in human carcinoma cell lines by up-regulating thymidine phosphorylase activity." (PMID 29488121, 2018). "We divided all GC patients into two groups according to the expression status of TYMP in cancer tissues." (PMID 27283904, 2016). "In the subgroup analysis, we furthermore found that, the prognostic significance of SII was duplicated in localized GC patients with different TYMP expression of cancer tissues and American Joint Committee on Cancer (AJCC) TNM classification." (PMID 27283904, 2016). "The dual roles of TYMP as a tumor growth factor and a key activation enzyme of anticancer metabolites resulted in a mixed outcome in cancer patients." (PMID 25881156, 2015). "High levels of thymidine kinase 1 (TK1) and thymidine phosphorylase (TYMP) are key molecular targets by thymidine therapeutics in cancer treatment." (PMID 25881156, 2015). "More importantly, our results in this study indicated that TYMP alone was a critical target to enhance the selectivity of a thymidine conjugate on cancer cells." (PMID 25881156, 2015). "More importantly, our in vitro studies demonstrated that the suppression of TYMP by shRNA significantly enhanced the selectivity of thymidine analog dT-QX on cancer cells that have high levels of TYMP and TK1." (PMID 25881156, 2015). "All these results indicated that suppression of TYMP by shRNA is an effective approach to enhance the selective cytotoxicity of dT-QX on cancer cells with high levels of TYMP and TK1." (PMID 25881156, 2015). "This selectivity arises from the differential expression of thymidine phosphorylase (TYMP) which converts capecitabine to 5-FU and which has significantly higher activity in cancer cells than in normal tissue 8,9." (PMID 24464780, 2014). "Inspecting this list, we found several genes, such as thymidine phosphorylase (TYMP), apoptosis-related cysteine peptidase (CASP10), and notch 4 (NOTCH4), have been implicated in cancer cells, but most of the gene are novel ones." (PMID 24171174, 2013). "Integration with publicly available single-cell sequencing data revealed that these proteins were mostly macrophage and monocyte-associated with malignant features (TYMP, FCER1G, FCGR1A, SYK, and F13A1), except NNMT, which was highest in cancer-associated fibroblasts (Table EV4)." (PMID 41233595, 2026).
cancer (continued). "In 2022, a research team explored whether demethylation of TYMP would increase cancer cell sensitivity to 5-FU." (PMID 40303404, 2025). "Despite its promising potential in cancer therapy, TYMP has certain limitations." (PMID 40303404, 2025). "Although TYMP inhibitors may hold promise in cancer therapy, their safety remains uncertain, and long-term research is necessary to determine their clinical viability." (PMID 40303404, 2025). "Consequently, studying TYMP enhances our understanding of cancer mechanisms and is vital for cancer treatment." (PMID 40303404, 2025). "Consequently, inhibiting TYMP enzymatic activity using TYMP inhibitors has emerged as a viable therapeutic approach for slowing cancer progression." (PMID 40303404, 2025). "As a molecular target, TYMP is being explored for the development of cancer therapeutics." (PMID 40303404, 2025). "Furthermore, plasma levels of TYMP in individuals with certain cancers are significantly higher than in healthy individuals." (PMID 40303404, 2025). "However, research has indicated that certain TYMP activities can activate a variety of chemotherapeutic agents, which is crucial for cancer therapy." (PMID 40303404, 2025). "Therefore, understanding the underlying mechanisms of cancer and identifying viable therapeutic targets, such as TYMP, has become an essential focus in cancer research." (PMID 40303404, 2025). "Ongoing research on TYMP could deepen our understanding of human physiology and the pathogenesis of cancer and open new avenues for therapeutic interventions." (PMID 40303404, 2025). "As such, TYMP has become a critical target in cancer research." (PMID 40303404, 2025). "Due to individual differences among patients, TYMP-targeting drugs may be effective for some cancer individuals, while less effective for others." (PMID 40303404, 2025). "Thymidine phosphorylase (TP) is an enzyme that is overexpressed in many types of cancer cells." (PMID 38164142, 2024). "Thymidine phosphorylase enzyme may also become activated by physical and chemical stress in the cancer tissue, that promotes the concentration of 2-deoxy-D-ribose, which is the causative factor for the progression of tumors." (PMID 37259401, 2023). "Moreover, TPI also induced apoptosis in CT-26 cells, indicating that TPI concurrently downregulated the expression of TYMP and inhibited the growth of CT-26 cancer cells." (PMID 36090972, 2022). "Many studies have indicated that TYMP was a potential target for cancer immunotherapy." (PMID 35250999, 2022). "Indeed, using cancer cell lines to confirm the TYMS dependency predicted by PARIS, we discovered that the most robust effects can be observed in those lines where TYMP is expressed at high levels and CDKN2A is mutated or deleted." (PMID 34454516, 2021). "Capecitabine is activated initially through hepatic metabolism and finally to 5-FU at the level of the cancer cell through the action of thymidine phosphorylase, also known as platelet-derived growth factor, which is expressed at higher levels in cancer cells than in the surrounding normal tissues." (PMID 33992087, 2021). "Although 3FC has been shown to suppress STAT3 signaling and induce growth inhibition in cancer cell lines in an in vivo model, earlier studies have demonstrated that 3FC can also modulate functions of many cancer-promoting proteins (such as thymidine phosphorylase and DNA topoisomerase IIα)." (PMID 35053027, 2021). "Thymidine phosphorylase (TP), an angiogenic protein and an enzyme required for the activation of several 5-fluorouracil (FU) prodrugs, is overexpressed by approximately 30–40% of cancers." (PMID 30380599, 2018). "High level of TYMP in cancer patients resulted in more aggressive cancer growth, higher incidence of vascular infiltration and metastasis and may thereby lead to unfavorable survival." (PMID 27283904, 2016). "The counteraction by TYMP could be overcome with RNA silencing to significantly enhance the dT-QX selectivity in cancer cells." (PMID 25881156, 2015).
cancer (continued). "Thus, dT-QX serves a chemical entity to investigate how TK1 and TYMP impact the activity in cancer cells." (PMID 25881156, 2015). "The key question would be whether TK1 and TYMP were involved in the cytotoxic action of dT-QX in cancer cells." (PMID 25881156, 2015). "Interestingly, several of these small and large altered regions contain cancer-associated genes known to be involved in CRC and/or the metastatic process: i.e. the TPD52, FABP5, MAP2K4, LLGL1, FBLN1 and TYMP genes." (PMID 21060790, 2010). "Moreover, TYMP holds substantial implications in cancer treatment and prognosis." (PMID 40303404, 2025). "Therefore, inhibiting TYMP could potentially alleviate endothelial dysfunction and enhance cancer treatment." (PMID 40303404, 2025). "Therefore, blocking TYMP represents a potential anti-cancer treatment strategy." (PMID 40519286, 2025). "Human mesenchymal stem cells are used as delivery vehicles to deliver a certain amount of TYMP activity to docifluridine, a prodrug of 5-fluorouracil, thereby converting the non-toxic prodrug docifluridine into the toxic chemotherapy drug 5-fluorouracil, thereby eliminating cancer cells." (PMID 40303404, 2025). "In cancer cells, high levels of ROS have been detected due to increased metabolic and peroxisomal activities, mitochondrial dysfunction, increased receptor signaling, oncogenic activity, increased enzymatic activity of oxidases, lipoxygenases, cyclooxygenases and thymidine phosphorylase." (PMID 35291987, 2022). "The effect of capecitabine after bevacizumab–paclitaxel induction therapy may be explained by the mechanism discussed in the CREATE-X trial report; taxanes may induce thymidine phosphorylase in cancer cells, which activates capecitabine, resulting in increased antitumor effect." (PMID 34503209, 2021). "It is also known as thymidine phosphorylase; its activity and expression in carcinomas of the esophagus, stomach, colorectum, pancreas, and lung are significantly higher than in the adjacent nonneoplastic tissue and may have an important role in the proliferation of these solid tumours." (PMID 26346854, 2015). "Thymidine phosphorylase expression in cancer cells might also influence their aggressiveness." (PMID 21386840, 2011). "Thymidine phosphorylase activity is commonly increased in malignant tissue across the common cancers and is specifically so in PDAC where increased thymidine phosphorylase levels correlated with shorter survival." (PMID 38524376, 2024). "The TYMP inhibitor Tipiracil (TPI), is commonly used in anti-cancer treatments to prevent the degradation of 5-FU and has been shown to prevent thrombosis." (PMID 37100811, 2023). "Our study also revealed the treatment-induced increase in CDA and TYMP expression is dependent on the chemotherapeutic drug, the treatment schedule and also on the genetic and EMT-status of the individual cancer cell." (PMID 33874986, 2021). "We retrospectively examined the CXI of 80 patients who were treated with trifluridine/thymidine phosphorylase inhibitor (FTD/TPI) + bevacizumab (Bmab) therapy as a later-line treatment for mCRC, and assessed the impact of cancer cachexia on chemotherapeutic efficacy using CXI." (PMID 39468284, 2024). "The focus of this review is to highlight the anticancer potential, molecular docking, and SAR studies of 1,3,4-oxadiazole derivatives by inhibiting specific cancer biological targets, such as inhibiting telomerase activity, HDAC, thymidylate synthase, and the thymidine phosphorylase enzyme." (PMID 37259401, 2023). "Furthermore, high TYMP expression levels and the effect on occurrence and progression were consistent with listing in the PRIDE database, The Cancer Genome Atlas (TCGA) data and with our proteomic data." (PMID 35314790, 2022).
cancer (continued). "Among chromone derivatives, 3-formylchromone (3FC) and its derivatives have been reported to induce cytotoxicity in various cancer models by targeting diverse cellular targets such as STAT3, thymidine phosphorylase, DNA topoisomerase IIα, and the reversing of multidrug resistance." (PMID 35053027, 2021). "Thus, thymidine synthase, thymidine phosphorylase, and DPD are known to be involved in the sensitivity of cancer cells to 5-fluorouracil." (PMID 34101751, 2021). "Blood tests and TYMP expression in cancer tissues were not performed for 10 patients respectively; one patient neither had data of blood test nor TYMP expression." (PMID 27283904, 2016). "Whether the absence of thymidine phosphorylase expression confers protection against cancer development remains to be determined." (PMID 41009664, 2025). "Furthermore, recent studies suggest that utilizing human mesenchymal stem cells (hMSCs) as carriers to deliver TYMP to cancer cells may facilitate the conversion of docifluridine (5′-DFUR) into the toxic 5-FU, promoting cancer cell death." (PMID 40303404, 2025). "In summary, exogenous thymidine phosphorylase expressed in hMSCs successfully converted the non-toxic prodrug doxifluridine into the chemotherapy agent 5-fluorouracil, effectively eliminating both cancer cells and hMSCs within a short period." (PMID 39768012, 2024). "TYMP is often deleted in many kinds of cancers but not in GC." (PMID 32887417, 2020). "Among them, we reported TYMP to be often deleted in several kinds of cancers but not in GC, while TYMS is frequently amplified, which may lead to treatment failure." (PMID 32887417, 2020). "Even though this decreasing trend in the amplified transcription of SAMHD1 at 24 h might result in loosening the regulation of CAD, DHODH and UMPS, the critical enzymes involved in direct influx of dTMP (TYMS and TYMP) did not appear to be recovered to normal levels in cancer cells." (PMID 36414668, 2022). "It is important to note that these cancer-specific transcriptional biomarkers were not particularly unique at the genetic copy number level, apart from extensive copy number gains for GFPT1 in LUSC, and overall CNAs for TYMP in HNSC." (PMID 36831501, 2023).
mitochondrial disease (11 papers, 2011 to 2023). "The benchmark for the diagnosis of MNGIE is the identification of homozygous or compound heterozygous allelic pathogenic TYMP variants, which are detected by Sanger or next generation gene sequencing, mitochondrial disease gene panels or whole exosome sequencing." (PMID 32914088, 2020). "Individuals harboring POLG-, TYMP-, or MPV17- deletions or m.8993T>G and m.8993T>C mtDNA mutations, as well as those affected by SURF1-related mitochondrial diseases are at greater risk of developing peripheral neuropathy." (PMID 33383961, 2020). "A growing number of mitochondrial diseases with mtDNA instability have been linked to mitochondrial deoxynucleotide pool imbalance, including deficiencies of TK2, dGK, RRM2B or TYMP." (PMID 29602790, 2018). "Also, patients with mitochondrial diseases affecting muscle argue against this (TK2, SUCLA2, SUCLG1, RRM2B, DGUOK, and TYMP)." (PMID 30538797, 2018).
genetic disorder (4 papers, 2019 to 2025). "Mutations in the TYMP gene can lead to genetic disorders such as MNGIE." (PMID 40303404, 2025).
metabolic disorder (3 papers, 2017 to 2021). "Mitochondrial neurogastrointestinal encephalomyopathy (MNGIE) is a progressive metabolic disorder caused by thymidine phosphorylase (TP) enzyme deficiency." (PMID 28261062, 2017). "Human thymidine phosphorylase (HsTP) is an enzyme with important implications in the field of rare metabolic diseases." (PMID 34976980, 2021).
adenocarcinoma (2 papers, 1993 to 2024). A common cancer characterized by the presence of malignant glandular cells. "The hMSCs were first transduced with thymidine phosphorylase-encoded lentiviral vectors produced by HEK293T cells, then co-cultured with A549 adenocarcinoma cells in the presence of doxifluridine." (PMID 39768012, 2024).